INS (insulin)
Diseases named in the same sentence as INS in open-access papers (continued):
Sharing a sentence is not in itself a finding about the gene and the disease.
diabetes (continued). "Perez Acadia used an artificial neural network to establish a predictive model of hyperglycaemia in diabetic patients; Zarkogianni K used an artificial neural network to establish a query system for insulin injection in people with diabetes." (PMID 31771577, 2019). "The non-interventional International Operations Hypoglycemia Assessment Tool (IO-HAT) study assessed the incidence of hypoglycemia in patients with insulin-treated diabetes across nine countries, including a cohort of patients in Colombia." (PMID 31584770, 2019). "Currently, PA is considered a real first-line therapy against diabetes for its activity in promoting insulin release and protecting against diabetes complications." (PMID 31557786, 2019). "Participants with DR had younger age, longer duration of diabetes, higher proportion of smoking, using oral medicine+insulin, having positive UACR, higher levels of SBP, HbA1c than those without DR (P < 0.05)." (PMID 30658647, 2019). "In older subjects, abnormalities in both insulin sensitivity and insulin secretion lead gradually to impaired glucose tolerance and consequently to clinically manifest diabetes." (PMID 30833929, 2019). "Mutations in HDAC4 disrupt the deacetylation of FoxO1, subsequently decrease the β‐cell function including insulin secretion, resulting in diabetes." (PMID 30968599, 2019). "Comparison with other people with diabetes was important, especially with those who had suffered from diabetes longer and needed treatment with insulin." (PMID 31126267, 2019). "In early stages of type 2 diabetes mellitus, pancreatic beta cells try to compensate insulin resistance of fat, muscle, and liver by elevated hormone secretion." (PMID 31827698, 2019). "Proxy measures for disease severity such as duration of diabetes, microvascular complications, being on insulin and number of antihypertensives display the strongest association with poor control in HbA1c, SBP and LDL-C." (PMID 31729951, 2019). "While both types of diabetes share similar symptoms, they can be distinguished by measuring endogenous insulin production." (PMID 30766472, 2019). "For women with pre-existing diabetes, the prevalence of metformin use has increased (20.4 to 41.5%) over the study period, while use of insulin decreased (89.8 to 77.3%)." (PMID 31775682, 2019). "In this review, we summarize the recent progress in aging-, and stress-induced β cell senescence, and its impact on β cell viability, insulin secretion and regeneration, as well as discuss its relevance to the development of diabetes mellitus." (PMID 31721726, 2019). "Beyond other types of diabetes, high levels of plasma glucose in ketosis-onset diabetes exhibited the acute blunted insulin secretion and an initial reduction in glucose disposal at the episode of ketoacidosis." (PMID 31049079, 2019). "Strategies for combating metabolic diseases through the activation of UCP1 have been proposed; for instance, eight subjects with diabetes reported a 43% increase in insulin sensitivity when UCP1 was activated by cold acclimation (14–15 °C) for 10 days." (PMID 31590292, 2019). "The duration of diabetes in all insulin-naive patients was significantly lower than that in all insulin-treated patients." (PMID 30807441, 2019). "In Black’s study of older Mexican American diabetes patients, “insulin” had the highest OR value (OR = 1.83; 95% CI: 1.30–2.59), followed by “both insulin and OHA (oral hypoglycemic agent)” (OR = 1.79; 95% CI: 1.10–2.89)." (PMID 31726788, 2019). "Oral agents and insulin injection had a significant correlation with depressive symptoms in diabetes patients." (PMID 31726788, 2019). "In particular, the depressive symptoms of patients with diabetes who were on pharmacologic treatments (oral agents, insulin injection, and both oral agent medications and insulin injection) were assessed in terms of sex." (PMID 31726788, 2019).
diabetes (continued). "The associated cardiometabolic factors of NWCO (by WC, WHtR and WHR) were hypertension, diabetes, insulin resistance, decreased insulin sensitivity, low high-density lipoprotein and elevated triglyceride." (PMID 30931996, 2019). "MMP-9 has been shown to cleave organ-specific aAg, such as myelin basic protein in multiple sclerosis, collagen in arthritis, insulin in diabetes, and ubiquitous aAg in systemic autoimmune diseases." (PMID 30967870, 2019). "The commonest mode of diabetes treatment was a combination of insulin and oral hypoglycaemic agents, in 67 (44.4%) of the participants." (PMID 31762905, 2019). "After diabetes induction, the serum insulin levels significantly decreased in diabetic rats compared to the healthy rats (P-value<0.001)." (PMID 32133058, 2019). "Subcutaneous injection of insulin can maintain glucose utilization at a rate of 1 mg/kg/min for 20 h, both in healthy subjects and in patients with diabetes mellitus." (PMID 31555212, 2019). "It has been reported that circRNA is involved in the regulation of insulin secretion and pathogenesis of diabetes." (PMID 30736847, 2019). "Conversely, the insulin levels were always lower in the Diabetes lean than in the Diabetes obese subgroup." (PMID 31828157, 2019). "Low insulin sensitivity and high diabetes rate have been observed in a 15-year follow-up in a group of BRCA mutation carriers who developed BC." (PMID 30949290, 2019). "The management of diabetes with insulin and synthetic oral hypoglycemic drugs can produce serious side effects and in addition, they fail to prevent diabetes related complications in many patients." (PMID 31142215, 2019). "Diabetes mellitus (DM) is a chronic disease characterized by hyperglycemia due to altered insulin secretion or action, or both." (PMID 31557786, 2019). "Although the etiology of diabetes is complex, the key factor is chronic hyperglycemia due to impaired β-cell function and insulin sensitivity." (PMID 31882596, 2019). "Type 2 diabetes mellitus (T2DM) is a metabolic disorder characterized by impaired insulin action and its secretion." (PMID 31569751, 2019). "Long‐term high‐fat diet deteriorates insulin sensitivity leading to diabetes and decreases longevity, and β‐cell dysfunction progresses to a reduction in mass is one of pathological fundaments in diabetes." (PMID 30644630, 2019). "In the future, more studies should be performed to investigate the potential of insulin and galangin to be used to prevent and manage diabetes mellitus." (PMID 30862104, 2019). "Diabetes mellitus (DM) on insulin is a patient-related factor in the assessment of surgical risk based on the EuroSCORE II and, as such, it confers additional risk on outcomes after transcatheter aortic valve implantation (TAVI)." (PMID 31138207, 2019). "T2DM, characterized by the combination of insufficient insulin secretion and insulin resistance, accounts for approximately 90% to 95% of all diabetes cases." (PMID 31682586, 2019). "The introduction of insulin therapy for the treatment of gestational hyperglycemia changed the history of pregnant women with diabetes." (PMID 30786308, 2019). "We chose to test for insulin AAb because it cannot be reliably tested for using the ELISA platform and is a common islet AAb in diabetes and, therefore, broadly relevant." (PMID 30730939, 2019). "Anti-diabetes therapy such as insulin, metformin, combination of insulin + an oral hypoglycemic agent or combination of metformin + an oral hypoglycemic agent for more than 6 months did not alter serum HN levels in our study cohort." (PMID 31214116, 2019). "Additionally, the presence of vitamin D receptors in the beta-cells further support the idea that vitamin D regulates insulin secretion at least partly, and its deficiency/insufficiency can result in decreased insulin sensitivity at the target tissues, thereby causing or worsening diabetes." (PMID 30641861, 2019).
diabetes (continued). "Insulin-treated diabetes mellitus was identified as variable that showed a trend towards a predictor for major adverse cardiac events." (PMID 30851731, 2019). "Patients with diabetes were treated with lifestyle modification (n = 44), oral antidiabetic agents (n = 43), or combination therapies with insulin (n = 2), resulting in adequate glycemic control (hemoglobin A1c 6.5 ± 0.9%)." (PMID 33681514, 2019). "Measurement of C-peptide, a surrogate marker of insulin secretion, allows robust diagnosis of type 1 diabetes in long-standing diabetes (>3 years duration) and closely relates to treatment requirements." (PMID 30969375, 2019). "Vascular insulin resistance also induces diabetes by impairing insulin-induced capillary recruitment and insulin delivery in skeletal muscle, and glucose-induced insulin secretion from β-cells." (PMID 31013778, 2019). "Diabetes patients who experienced hypoglycemic events had a high prevalence of comorbidities, disabilities, and malnutrition, and were often treated with insulin therapy and use of polypharmacy." (PMID 30845785, 2019). "The goal is to determine if short-term elevation of norepinephrine would affect insulin secretion and glucose disposal in subjects with non-insulin-dependent diabetes mellitus (NIDDM)." (PMID 31485387, 2019). "Currently, worldwide, DM1 represents 5% to 10% of all diabetes cases, however, the use of insulin is not limited to only those people afflicted with DM1." (PMID 31798448, 2019). "Four patients with PHEO had diabetes (two of them were on insulin and three of them were on oral antidiabetic drugs) and seven patients in both groups were treated for dyslipidemia." (PMID 30845735, 2019). "Another point of attention is that 13.5% of our studied population has diabetes mellitus and uses insulin for therapy with potential interference with our cardiovascular measurements." (PMID 31109316, 2019). "Insulin therapy has been used to treat diabetes, but it can have side effects such as hypoglycemic episodes." (PMID 31839754, 2019). "The same study found significantly better diabetes management and insulin-related attitudes and beliefs toward the digital education intervention in the intervention group." (PMID 30789348, 2019). "In this study, insulin glargine and insulin analogue acarbose were used in elderly patients with diabetes, and the effect of treatment was analyzed." (PMID 31258562, 2019). "The observations that ELVs are largely dysregulated in diabetes and that exosomal cargo components regulate β-cell function and insulin signaling in recipient cells make them attractive therapeutic targets in treating T2DM." (PMID 30993115, 2019). "In the linagliptin CARMELINA trial, 6991 patients with type 2 diabetes and at high CVD and renal risk were randomly assigned to linagliptin or placebo, in addition to other diabetes medications (predominantly metformin, sulfonylurea and insulin)." (PMID 31366085, 2019). "The “incretin effect” (increased stimulation of insulin elicited by oral administration of glucose) is proven to be significantly lower in diabetes mellitus compared to healthy subjects after a meal." (PMID 31575077, 2019). "NS was showed to improve laboratory parameters of hyperglycemia and diabetes control with a significant fall in fasting blood glucose, and a significant rise in serum insulin." (PMID 31817324, 2019). "Diabetes mellitus (DM) is characterized by hyperglycemia due to changes in the production or action of insulin; the chronicity of this condition is associated with damage, dysfunction, and insufficiency of target systems such as cardiovascular and central nervous systems." (PMID 30944699, 2019). "Several studies have suggested possible mechanismsfor GDM offspringto develop diabetes, including an abnormal insulin signaling pathway, lower antioxidant capacity, lipid metabolism disorder, and epigenetic alterations." (PMID 31340612, 2019).
diabetes (continued). "The insulin levels at fasting and 120 min after glucose administration were significantly lower in the Diabetes HB group than in the obesity subgroup of the Diabetes group." (PMID 31828157, 2019). "Suppression of HDAC3 enhances oxidative metabolism, regulates gluconeogenesis, reduces hyperglycaemia, and increases insulin secretion, which are conductive in improving diabetes." (PMID 30906786, 2019). "T1D, also known as juvenile or insulin-dependent diabetes mellitus (IDDM), is typically caused by an absolute deficiency of insulin secretion." (PMID 31049023, 2019). "We defined diabetes as self‐reported use of insulin/oral hypoglycaemics or fasting (random) glucose ≥7.0 (≥11.1) mmol." (PMID 30990252, 2019). "For instance, a study in northern Finland shows that self-poisoning was the commonest method 48% and another study in the USA found that diabetes-related methods like insulin overdose are most common." (PMID 31455263, 2019). "In support of this concept, antagonising glucagon receptor (GCGR) signalling can improve insulin sensitivity in experimental models of diabetes and obesity." (PMID 30626440, 2019). "One example is the idea of creating an exchange mechanism to share diabetes supplies (e.g., insulin or testing strips)." (PMID 31366047, 2019). "The average insulin cost increased three-fold from 2002 to 2013, with availability and rising costs having an impact on diabetes patients and health systems worldwide." (PMID 31798448, 2019). "Despite the widely known fact of multiple benefits of adherence to insulin therapy, poor adherence among patients remains a common problem in substantial number of patients with diabetes mellitus." (PMID 31692777, 2019). "Most staff also saw value in MITI beyond insulin titration, including MITI’s ability to engage with patients in between visits and potentially increase medication adherence by reminding the patients to attend to their diabetes and use their insulin daily." (PMID 31368439, 2019). "An ADA workgroup and an ADA consensus conference on diabetic kidney disease have suggested that clinicians should exercise precaution when selecting and dosing SU and insulin for patients with diabetes and CKD." (PMID 30813549, 2019). "Diabetes mellitus (DM) is a metabolic ailment resulting from insulin resistance or the reduced secretion of insulin." (PMID 31191707, 2019). "In keeping with prior studies, we found that patients with diabetes had more echocardiographic left ventricular hypertrophy than those without and this was especially true for patients treated with insulin." (PMID 31271255, 2019). "Rosiglitazone has many advantages in treating patients with diabetes, including increasing insulin sensitivity, reducing blood glucose and hemoglobin A1c levels, inhibiting adipose tissue lipolysis hormones, and inhibiting inflammation." (PMID 31160894, 2019). "Apart from these processes, mounting evidence suggests that specific features of diabetes, namely impaired glucose metabolism and insulin signaling in the brain, play a key role in AD." (PMID 31293498, 2019). "The purpose of this study is to look at the effect of some penetration enhancers on in vivo permeation of insulin and insulin sensitizers (curcumin and rutin) through diabetes-induced mouse skin." (PMID 31067805, 2019). "Human insulin knock-in mice, both homozygous and heterozygous, had a significantly reduced incidence of diabetes (p<0.0001, Log-rank test) compared to wildtype NOD mice when cohorts were followed for 300 days." (PMID 31821343, 2019). "One patient (patient 7) who underwent surgery at two months of age developed diabetes mellitus at five years of age and was treated with insulin." (PMID 31208162, 2019). "The improvement of the insulin sensitivity by rosmarinic acid was previously demonstrated in rats in various diabetes models." (PMID 30691017, 2019).
diabetes (continued). "Insulin plays a key role in glucose homeostasis and is hence used to treat hyperglycemia, the main characteristic of diabetes mellitus." (PMID 31382473, 2019). "The DCM education tools focus on four different domains related to successful diabetes self-management such as 1) living with diabetes, 2) how diabetes works, 3) healthy eating and keeping active, and 4) starting insulin." (PMID 31286927, 2019). "TZDs are synthetic PPARγ ligands that modulate metabolic homeostasis and improve glucose tolerance in diabetes by increasing insulin sensitivity." (PMID 30729133, 2019). "Engaging in regular physical activity among people living with diabetes contributes to cardiorespiratory fitness, improved glycaemic control, decreased insulin resistance, improved blood lipid profile and improved blood pressure." (PMID 40078796, 2019). "Rather, treatments focus on restoring or replacing the functions lost due to the pathology of the disease, for instance, insulin replacement therapies for the treatment of diabetes." (PMID 31388355, 2019). "In the mentioned study, the participants had diabetes or prediabetes, in which the observed impairment of insulin secretion, especially first-phase secretion, is more severe than in young PCOS women." (PMID 31307012, 2019). "The pancreatic β cell harbors an exemplary nutrient sensing machinery coupled to insulin secretion, which controls glucose homeostasis in normal conditions and is disturbed in diabetes." (PMID 31346174, 2019). "Type 1 diabetes mellitus (T1D) is an autoimmune disorder characterized by the destruction of insulin-producing ß-cells in the pancreas, resulting in a life-long dependence on exogenous insulin." (PMID 31399563, 2019). "In this present study, it was found that the most frequently consulted therapy team member was the diabetes nurse and the most frequently issue consulted about was insulin dose and blood glucose regulation (42.7%)." (PMID 30015620, 2019). "Further investigation is required to determine the relationship between the animal’s metabolic status and insulin-mTOR signaling, especially in pathophysiological states, such as obesity or diabetes." (PMID 31714935, 2019). "When we restricted our set of diabetes cases to individuals prescribed metformin (7,923 of 13,982 individuals) or insulin (2,094 of 13,982 individuals), while using the full set of control individuals, odds ratios were again similar." (PMID 31821322, 2019). "In this type of diabetes, the body produces sufficient amount of insulin but due to cellular resistance, it remains ineffective." (PMID 30962863, 2019). "First-degree relatives of patients with diabetes (FDR) tend to have impaired insulin activity, which lead to the alternation of circulating cytokine levels." (PMID 31795988, 2019). "This is the first study to comprehensively examine the prescribing practices and factors of influence of specialist diabetes healthcare professionals regarding insulin initiation in T2D across Central and South-Eastern European countries." (PMID 30993528, 2019). "Patients with diabetes are advised to present approximately 90 min prior to their scheduled scan to minimise disruption to workflow by allowing time for insulin administration if necessary." (PMID 30737563, 2019). "Monogenic Diabetes is relatively rare, representing only 1-2% of total diabetes cases; nevertheless, it is often misdiagnosed primarily as type 1 diabetes, leading to unnecessary insulin therapy and delayed recognition of affected family members." (PMID 31110826, 2019). "We explored prescription of non-insulin diabetes medications in primary care for a large sample of people with T2D and renal impairment." (PMID 30777033, 2019). "Fekadu and collaborators in Ethiopia found a male preponderanceand poor socioeconomic conditions in their insulin requiring patients in theirstudy of the atypical diabetes phenotypes." (PMID 31673335, 2019).